ENSG00000285404 (novel protein, DEPDC5-YWHAH readthrough)
Gene: Protein-coding gene on chromosome 22 (31,754,899 to 31,956,243, forward strand). Ensembl gene ENSG00000285404.
Genetic constraint (gnomAD): Loss-of-function variants: 26 observed, 77.65 expected, observed/expected ratio (o/e) 0.33, 90% interval 0.24 to 0.47. Missense variants: 584 observed, 747.55 expected, observed/expected ratio (o/e) 0.78, 90% interval 0.73 to 0.84. Synonymous variants: 249 observed, 265.88 expected, observed/expected ratio (o/e) 0.94, 90% interval 0.84 to 1.04.